FGFR3 (fibroblast growth factor receptor 3)
Diseases named in the same sentence as FGFR3 in open-access papers (continued):
Sharing a sentence is not in itself a finding about the gene and the disease.
bladder cancer (continued). "Specifically in bladder cancer, these FDA‐approved, companion diagnostic biomarkers are FGFR3 mutation and FGFR2/3 fusion." (PMID 34114376, 2021). "In our previous study, MPT0L145 arrested cell proliferation through inhibition of the phosphorylation of FGFR1 and FGFR3 in bladder cancer cells." (PMID 34885226, 2021). "A direct interaction between FGFR3 and TAK1 increases with mutations in FGFR3 known to occur in MM and bladder cancer." (PMID 34068954, 2021). "At the same time, advances in the understanding of the molecular biology of bladder cancer have led to the identification of molecular pathways, such as FGFR3 signaling, upon which new therapeutic approaches can be targeted." (PMID 34984415, 2021). "We also found that FGFR3, a member of the bladder cancer signaling pathway, was significantly downregulated, indicating an aggressive characteristic and a worse prognosis." (PMID 33535616, 2021). "FGFR3 mutations are the most common FGFR aberration in urothelial cancers and lung squamous cell cancer, and are common in cervical and bladder carcinomas." (PMID 34068954, 2021). "We have demonstrated that ctDNA profiling can identify previously proposed biomarkers for therapy response in bladder cancer, including alterations in FGFR3, ERCC2, and ERBB2, and TMB." (PMID 33420073, 2021). "Among the top DMRs, we note many overlapping with genes known to be involved in bladder cancer, such as FGFR3, GATA3, KRT15, and KRT5." (PMID 33397444, 2021). "Given the potential and challenges ICIs on their own, it is possible that the coacting combination of potent ICIs and specific FGFR3 inhibitors can offer much-needed improvements in targeted therapeutics for bladder cancer." (PMID 34984415, 2021). "FGFR3 was identified as a key oncogene in many types of tumors, especially multiple myeloma and bladder cancer." (PMID 33584313, 2020). "In particular, this receptor subtype is involved in bladder cancer and salivary adenoid cystic cancer, in which significant amplifications of FGFR3 have been found." (PMID 33352931, 2020). "Actionable FGFR3 gene fusions were found to be relatively common in glioblastoma and bladder cancer." (PMID 32726920, 2020). "We review the role of FGFR3 in bladder cancer and discuss preclinical and clinical clues of its effectiveness as a patient selection factor and therapeutic target in the era of immunotherapy." (PMID 33224141, 2020). "Mao et al38 discovered that miR‐181a‐5p interacts with fibroblast growth factor receptor 3 (FGFR3) to promote the progression of bladder cancer through the activation of the STAT3 pathway." (PMID 33002329, 2020). "It turned out that low FGFR3 expression in combination with high PD-L1+ status predicted bad survival of patients with primary luminal non-invasive bladder cancer." (PMID 33238591, 2020). "Recent studies have demonstrated that FGFR3 alterations commonly occur in up to 21% of locally advanced or metastatic bladder cancer, offering the possibility of new FGFR-targeted therapies." (PMID 32325639, 2020). "FGFR3 is involved in tumorigenesis in ∼40% of invasive bladder cancer and in the majority (∼80%) of low-grade non-invasive (stage Ta) bladder cancers." (PMID 32397531, 2020). "FGFR3 gene amplification (0.31%) has been observed in breast carcinoma, bladder carcinoma, glioblastoma multiforme, pancreatic cancer, and lung adenocarcinoma." (PMID 32962091, 2020).
bladder cancer (continued). "Patients with FGFR3 mutation and low MATH value exhibit longer overall survival time than that of all BLCA patients (p = 0.044), which was replicated in another bladder cancer database composed of 109 BLCA patients." (PMID 33243261, 2020). "Taken together, we verified that low MATH value was an independent favorable prognostic biomarker in FGFR3-mutant patients in another bladder cancer cohort." (PMID 33243261, 2020). "HRAS lies downstream of FGFR3, and increased signaling following mutations in HRAS are correlated with enhanced susceptibility to bladder cancer and other abnormalities in patients with Costello syndrome." (PMID 30670749, 2019). "The results indicated that immunoliposomes can specifically deliver the fluorescent molecules, Dio into bladder cancer cells highly expressing FGFR3." (PMID 31535232, 2019). "In this study, we investigate a transcription factor of the ETS-family, ETV5, as a putative effector of FGFR3 signalling in bladder cancer." (PMID 30952872, 2019). "Numerous functional studies silencing or targeting mutant FGFR3 in bladder cancer cell lines have shown decreased cell proliferation and tumorigenic potential both in vitro and in vivo." (PMID 30952872, 2019). "BAI1-associated protein 2–like 1 (also known as insulin receptor kinase substrate) is a fusion partner with FGFR3 in bladder cancer." (PMID 31007851, 2019). "The mutational state of TERTp and FGFR3 genes in bladder cancer is considered a promising predictor of recurrence of NMIBC, demonstrated by the association between FGFR3 mutation in primary tumor and later in recurrence events." (PMID 31921291, 2019). "Previous studies revealed that mTOR, HOXA1, and IGFBP1 were targeted by miR-99a in breast cancer; FGFR3 was targeted by miR-99a in bladder cancer; in the present study, we identified FGFR3 as a direct target of miR-99a in breast cancer for the first time." (PMID 32038996, 2019). "Several studies and the cohort presented here show that FGFR3 and RAS mutations are mutually exclusive events in bladder cancer." (PMID 31369573, 2019). "This is important because confirmation of “oncogene addiction” (reviewed in14,15) to mutant HRAS or interrelated components of the FGFR3 or PI3K/AKT/mTOR pathways would allow development of targeted approaches to treat noninvasive bladder cancer." (PMID 30670749, 2019). "This pathway is activated in around 40% bladder cancer cases (FGFR3: > 10%, EGFR:> 10%, ERBB2:~ 10%, ERBB3:~ 10%, NRAS/HRAS/KRAS:~ 10%, PTEN: ~ 10%, AKT3:~ 10%)." (PMID 31665050, 2019). "Our data therefore identify MYC as a master regulator of proliferation activated downstream from FGFR3 and as a positive regulator of FGFR3 expression in bladder cancer lines." (PMID 29463565, 2018). "More recently, a combination of methylation status of TWIST, ONECUT2, and OTX1 with mutational analyses of FGFR3, TERT, and HRAS has been reported to detect bladder cancer with a sensitivity of 97% and a specificity of 83%." (PMID 29907142, 2018). "Disruption of this FGFR3/MYC loop in bladder cancer cell lines by treatment with FGFR3, p38, AKT, or BET bromodomain inhibitors (JQ1) preventing MYC transcription decreased cell viability in vitro and tumor growth in vivo." (PMID 29463565, 2018). "We investigated the signals downstream from FGFR3 responsible for the observed higher levels of MYC mRNA and greater MYC protein stability in bladder cancer cells harboring FGFR3 mutations." (PMID 29463565, 2018). "Fibroblast growth factor receptor 3 (FGFR3) is amplified, translocated or mutated in a number of different human cancer types, but most commonly in bladder cancers." (PMID 29423038, 2018).
bladder cancer (continued). "Clinically, it would be beneficial to explore FGFR3 inhibition together with the concurrent immune modulators, such as BCG, as a potential treatment strategy for FGFR3‐mutated or ‐overexpressing bladder cancer at an early stage." (PMID 30043421, 2018). "Urinary protein levels of FGFR3 and Cyclin D3 were analyzed by Western blotting in 321 bladder cancer follow-up patients and 150 healthy control samples." (PMID 30544619, 2018). "We identified MYC as a key master regulator of proliferation activated by aberrantly activated FGFR3 in bladder cancer‐derived cell lines." (PMID 29463565, 2018). "In this cohort, 87/142 patients (61.3%) showed a high Ki67-index (≥15% positivity) and 100/142 bladder cancer patients (70.4%) were characterized by strong FGFR3 expression (Tomlinson Score 3)." (PMID 30154342, 2018). "Fibroblast growth factor receptor 3 (FGFR3) also stimulates SCD1 expression to accelerate tumor growth via activating SREBP1 in bladder cancers." (PMID 29907133, 2018). "We also demonstrated that the activation of both p38 and AKT was critical for the induction of bladder cancer cell proliferation and transformation by FGFR3." (PMID 29463565, 2018). "At nanomolar levels BGJ398 kills bladder cancer cells overexpressing wild-type FGFR3 (e.g. RT112, RT4, SW780, and JMSU1), but requires more than 3 μM to kill cells lacking this receptor." (PMID 29861860, 2018). "In this study, we aimed to characterize the aberrantly activated FGFR3 signaling pathways involved in bladder cancer cell growth/transformation." (PMID 29463565, 2018). "To gain insight into the oncogenic mechanism of FGFR3 in bladder cancer, we constructed FGFR3-related molecular networks." (PMID 28320388, 2017). "Further in vitro study is required to establish the functional role of DAPK1 in FGFR3-activating bladder cancer." (PMID 28388658, 2017). "Here, we explored the possible mechanism how FGFR3 signaling mediates bladder cancer development and progression by bioinformatics methods." (PMID 28320388, 2017). "We found that the expression levels of 2855 genes were altered upon the depletion of FGFR3 in bladder cancer cell line." (PMID 28320388, 2017). "BGJ398 (Novartis) is an additional potent, pan-FGFR inhibitor currently undergoing Phase I/II clinical trials after initially demonstrating antitumor activity in RT112 bladder cancer xenografts models overexpressing wild-type FGFR3." (PMID 28030802, 2017). "To address this question, we examined the correlation between FGF-2 and FGFR-3 expression or FGF-2 expression and FGFR-3 genetic alterations in a set of 129 bladder carcinomas in the TCGA database for which curated sequence data were available." (PMID 28515962, 2017). "Specifically, FGFR3 gene is reported to be involved in Bladder cancer based on the result (hsa05219) from the KEGG pathway mapping database." (PMID 27766936, 2016). "We examined the anti-growth effects of MPT0L145 on bladder cancer cells with different genetic background of FGFR3." (PMID 27029060, 2016). "Activation of fibroblast growth factor receptor 3 (FGFR3) has been reported to play important roles in several malignancies, including uterine cervix carcinoma and multiple myeloma as well as bladder cancers (BC)." (PMID 27930669, 2016). "In view of these aberrant alternations, FGFR3 is recognized as a unique potential therapeutic target for bladder cancer patients." (PMID 27029060, 2016). "FGFR3 plays a critical role in bladder cancer from low-grade stage, which is characterized by low levels of protein synthesis and high cell cycle gene activity." (PMID 26924873, 2016).
bladder cancer (continued). "MFGR1877S (developed by Genentech) is a human anti-FGFR3 monoclonal antibody that inhibits tumor progression of bladder carcinoma and multiple myeloma xenografts in mice by antagonizing FGFR3 signaling." (PMID 27007053, 2016). "With respect to protein expression, correlation of FGFR3 overexpression with low-grade and low-stage bladder cancers has been reported." (PMID 27154171, 2016). "Other researchers have demonstrated that a single-chain anti-FGFR3 Fv fragment fused to a toxin gene product, rGel, had the ability to inhibit the growth of a xenograft bladder cancer cell line." (PMID 27056048, 2016). "To date, it has been reported that some oncogenes play crucial role in the progression of bladder cancer, such as fibroblast growth factor receptor 3 (FGFR3), DEP domain–containing 1 (DEPDC1), M-phase phosphoprotein 1 (MPHOSPH1), and P73." (PMID 26905879, 2016). "FGFR-3 has been shown to play an important role in bladder cancer growth and is suggested as a candidate for targeted therapy." (PMID 26465941, 2015). "TACC3 levels are altered in several human cancers, for example, ovarian, non-small cell lung cancer, and bladder, and fusions between TACC3 and FGFR3 are reported in glioblastoma and bladder cancer." (PMID 26090906, 2015). "Down-regulated miRNA-99a can act as a tumor suppressor by inhibiting cell proliferation, migration and invasion by targeting fibroblast growth factor receptor 3 (FGFR3) in bladder cancer." (PMID 25991007, 2015). "In bladder cancer cells, FGFR3 expression directly correlates with an epithelial-like state whereas FGFR1 expression correlates with a more mesenchymal-like state." (PMID 25596738, 2015). "FGFR3 is frequently overexpressed in myeloma, ovarian and bladder cancers, suggesting its role in tumorigenesis." (PMID 26078354, 2015). "We find that TAK1 can activate NFκB nuclear localization (p65) and transcriptional activity downstream of FGFR3 in both MM and bladder cancer cells." (PMID 24466111, 2014). "FGFR3 was significantly downregulated in the bladder cancer T24 and EJ cell lines subsequent to overexpression of miR-99a (P<0.05)." (PMID 24944696, 2014). "In summary, to the best of our knowledge, the present study was the first to show that miR-99a regulates FGFR3 and contributes to cell proliferation, migration and invasion in bladder cancer." (PMID 24944696, 2014). "We have recently demonstrated that miR-100 is under-expressed in 100% of low-grade, non-invasive bladder cancers, with FGFR3 as a putative target gene, representing a possible first step of tumorigenesis, before the typical FGFR3 mutation." (PMID 25493074, 2014). "For example, FGFR3 displayed r>0.7 in four cancers (bladder cancer, glioblastoma, lung squamous, and melanoma) but r<0.5 in other cancers." (PMID 24874471, 2014). "Previously, in one of the publications based on our GWAS for bladder cancer risk, we described association of the rs798766[T] allele (TACC3/FGFR3 locus) with an increased risk of disease recurrence among low-stage low-grade NMIBC cases." (PMID 24586564, 2014). "Our aim is to analyze the role of miR-100 in bladder cancer cell lines in controlling the expression of some of its possible target genes, including FGFR3 and its relationship with proliferation, apoptosis and DNA ploidy." (PMID 25493074, 2014). "Immunohistochemical staining for FGFR3 in a panel of 126 bladder cancer tumors revealed intense staining in 20 (15.9%) samples and moderate staining in 42 (33.3%) samples." (PMID 24944696, 2014). "The results of the present study indicated that miR-99a suppressed bladder cancer cell proliferation, migration and invasion by the downregulation of FGFR3." (PMID 24944696, 2014).
bladder cancer (continued). "First, the growth factor receptor signaling pathway in bladder cancer (FGFR3), as defined in the review by Fendler et." (PMID 23717626, 2013). "Hereafter, we focus on the impact of the MAPK network in urinary bladder cancer, with particular emphasis on the differential behaviour between EGFR over-expression and FGFR3 activating mutation." (PMID 24250280, 2013). "Altogether, these analyses provided novel insights into the mechanisms differentiating the response of urinary bladder cancer cells to EGFR versus FGFR3 stimuli." (PMID 24250280, 2013). "All three compounds were found to be cytotoxic and/or cytostatic on a range of FGFR3- or FGFR1-dependent bladder cancer cell lines in vitro and to reduce FGFR phosphorylation and downstream signalling, with PD173074 and TKI258 showing the greatest effect." (PMID 22899908, 2012). "This study indicates that the FGFR3 urine assay, which was originally developed to monitor bladder cancer, is also a useful tool for diagnosing upper urinary tract cancer in a real-life setting." (PMID 22873290, 2012). "In order to identify genes up- or down-regulated during bladder cancer progression, the two pathways of the “FGFR3 model” were analyzed separately." (PMID 22724020, 2012). "An anti-FGFR3 monoclonal antibody that inhibited not only wild-type FGFR3, but also various mutants of the receptor, exerted potent antitumor activity against bladder carcinoma and multiple myeloma xenografts in mice." (PMID 22701813, 2012). "The human single-chain variable fragment (Fv) directed against FGFR3 blocked the proliferation of bladder carcinoma cells in vitro and in vivo." (PMID 22701813, 2012). "Here we describe a case in which a urine-based FGFR3 genetic test, (CertNDxTM Bladder Cancer Assay [Predictive Biosciences, Lexington, MA, USA]) was pivotal in diagnosing an upper urinary tract carcinoma that was difficult to diagnose by cytology or endoscopy." (PMID 22873290, 2012). "Other genetic alterations in FGFR3 include gene amplification in bladder cancer and translocation in myeloma." (PMID 22240789, 2012). "For further experiments we decided to work with the two UC cell lines RT112 (overexpressing FGFR3) and T24 (oncogenic H-Ras, homozygous PTEN mutation), both exhibiting frequently found genomic alterations in bladder cancer." (PMID 22110663, 2011). "Pathway analysis of affymetrix data file shows upregulation of four genes ERBB2, DAPK1, FGFR3 and CDKN2A which have reference to prove their involvement in causing bladder cancer." (PMID 22276047, 2011). "Accumulating data suggest that FGFR3 is a therapeutic target in both multiple myeloma and bladder cancer." (PMID 20234367, 2010). "In bladder cancer cells, knockdown of FGFR3 was achieved by short hairpin RNA constructs, leading to decreased proliferation, reduced clonogenicity and soft agar growth." (PMID 20234367, 2010). "Recent studies have suggested that FGFR3 has a significant function in the pathogenesis and progression of some malignancies including thyroid carcinoma, bladder carcinoma, multiple myeloma, and peripheral T-cell lymphoma." (PMID 19888223, 2009). "For example, the database BoostDM only covers FGFR3 based on mutational data from bladder cancer and provides no information at all for FGFR1, FGFR2 or FGFR4." (PMID 41361008, 2026). "Similarly, FGFR3V555M is a gatekeeper mutation that has been observed as a mechanism of clinical resistance to erdafitinib in FGFR3+ bladder cancer." (PMID 41584352, 2026).